IL6 (interleukin 6)
Diseases named in the same sentence as IL6 in open-access papers (continued):
Sharing a sentence is not in itself a finding about the gene and the disease.
ovarian carcinoma (520 papers, 1995 to 2026). A malignant neoplasm originating from the surface ovarian epithelium. "In patients with ovarian cancer, elevated levels of IL‐6 are associated with poor survival and chemoresistance." (PMID 40968783, 2026). "In this discussion, we will explore the coordinated role of IL6 in the development, metastasis, recurrence, and metabolic changes associated with ovarian cancer (OC)." (PMID 40427188, 2025). "IL-6 demonstrated strong diagnostic and prognostic potential, reaching an AUC of 1.000 in ovarian cancer when used alone or with VEGF-A and was associated with poorer survival when elevated alongside TNF-α." (PMID 41010973, 2025). "The CD74, CXCL1, and IL-6 released from surrounding cancer-associated mesenchymal stromal cells (CA-MSCs) have been reported to increase cancer stem cells of ovarian cancers." (PMID 40507922, 2025). "In agreement with our data, elevated IL-6 levels in serum and plasma have been widely documented in ovarian cancer patients and are associated with poor prognosis." (PMID 41149076, 2025). "A high neutrophil-to-lymphocyte ratio (NLR) has been identified as a poor prognostic factor in ovarian cancer, with increased IL6 levels being associated with a higher NLR and worse clinical outcomes." (PMID 40427188, 2025). "Research has found that IL6 levels are associated with the stage and grade of ovarian cancer, providing a certain reference value for its diagnosis." (PMID 40661780, 2025). "This approach would allow for the evaluation of IL6’s sensitivity, specificity, and ability to detect ovarian cancer at earlier stages, particularly in high-risk individuals." (PMID 40427188, 2025). "Elevated IL6 has been linked to chemotherapy resistance in ovarian cancer by activating pro-survival signaling pathways, such as JAK/STAT3 and PI3K/AKT, which enable tumor cells to withstand chemotherapy-induced stress." (PMID 40427188, 2025). "NETs formation in early-stage ovarian cancer has been shown to be associated with serum IL-6 and G-CSF." (PMID 40391215, 2025). "Several lines of evidence documented that IL-6 levels in the serum and peritoneal fluids are higher in ovarian cancer patients, and high level of IL-6 is independently associated with poor prognosis and survival of these patients." (PMID 38575576, 2024). "In ovarian cancer, studies highlighted the association of IL6 with a high neutrophilic/lymphocytic ratio, which is indicative of poor prognostic factors." (PMID 39766086, 2024). "In ovarian cancer cells, miR-1305 was reported to regulate dormancy linked to the IL-6 soluble factor by controlling the expression of the ARH-I gene, a tumor suppressor gene known for inducing autophagy in a nutrient deprivation environment." (PMID 39769441, 2024). "Another investigation on ovarian cancer patients suggests that elevated IL-6 levels are associated with shorter survival times, and reveals a negative relationship between CD45+CD14+PD-L1+ cells and IL-6 levels." (PMID 39690423, 2024). "Cytokines such as Interleukin 6 in ascites have also been found to have higher sensitivity and specificity as a diagnostic marker for ovarian cancer." (PMID 37007072, 2023). "In the tumor-associated ascites of patients with ovarian cancer, IL-6 stimulates Tregs’ expression of TNFR2." (PMID 36831623, 2023). "Logistic regression equation analysis suggests that serum IL‐6 is the influencing factors for patient recurrence and the ROC curve shows that serum IL‐6 levels have a certain diagnostic effect (AUC = 0.674) on ovarian cancer recurrence." (PMID 37904699, 2023). "For instance, in ovarian cancer, the administration of IL-6 neutralizing antibodies causes EGFR upregulation, while the combination of IL-6 neutralizing antibodies with Gefitinib, an EGFR inhibitor, promotes relevant anticancer activity." (PMID 36639824, 2023). "CAF-released IL-6 causes EMT in ovarian cancer cells, tumor growth, and ECM reorganization, mainly by mediating STAT3 phosphorylation." (PMID 36831623, 2023).
ovarian carcinoma (continued). "We aimed to investigate the anti-IL-6 activity of butein in ovarian cancer and elucidate the underlying molecular mechanisms." (PMID 37047012, 2023). "In advanced-stage ovarian cancer, higher cortisol levels (area under the curve) are associated with elevations in depressive symptoms and proinflammatory cytokine interleukin-6 (IL-6) and greater evening cortisol levels." (PMID 37746277, 2023). "Apart from this, ovarian cancer-associated exosomes can also produce IL-6 from monocytes and activate the STAT3 pathway to protect cancer cells from immune attack." (PMID 35681617, 2022). "Ovarian cancer-associated mesenchymal stem cells (CA-MSC) in the tumor microenvironment promote tumorigenesis through the secretion of factors including interleukin-6 (IL6) and the related cytokine leukemia inhibitory factor (LIF)." (PMID 36230597, 2022). "The phenomenon of paraneoplastic thrombocytosis observed in ovarian cancer was also linked to an increase in hepatic thrombopoietin in response to tumor-derived IL-6 production." (PMID 35740550, 2022). "Because of a significant association between IL-6 staining and poor prognosis in an immunohistochemical analysis of ovarian cancer tissue, IL-6 was identified as a therapeutic target." (PMID 35054524, 2022). "In human ovarian cancer and glioma cancer, tumor-associated Tregs trigger macrophages to secrete IL-10 and IL-6, which activate STAT3 and induce B7-H4 transcription." (PMID 35410218, 2022). "Overexpression of IL-6 can promote proliferation and invasion of ovarian cancer cells and has been associated with poorer prognosis." (PMID 36230617, 2022). "Elevated IL-6 levels in serum and ascites have been shown to be associated with impaired cancer cell sensitivity to chemotherapy and poor prognosis in ovarian cancer patients." (PMID 35681617, 2022). "Loss of Rb leads to an increase in IL-6 production recently involved in the appearance of PGCCs in ovarian cancer." (PMID 35458542, 2022). "Our results showed that IL-6 -174G>C is significantly associated with increased risk of ovarian cancer in the Iranian population." (PMID 34582655, 2021). "Statistically significant association of the IL-6 -174G>C CC genotype (OR= 3.231, 95% CI: 1.130-9.239, p=0.029) and C allele (OR = 1.915; 95%CI: 1.266-2.896, p=0.002) with the increased risk of ovarian cancer was found." (PMID 34582655, 2021). "While different ovarian cancer cell lines were utilized in the studies, interleukin-6 (IL-6) was examined to varying degrees in all three studies, likely due to its known roles in ovarian cancer progression and its association with the induction of cachexia." (PMID 33718372, 2021). "A number of studies have shown that IL-6 -174G>C (rs1800795) and -572C>G (rs1800796) polymorphisms have a role in the predisposition to gynecological malignancies including cervical and ovarian cancers." (PMID 34582655, 2021). "In summary, this study showed that IL-6 -174G>C polymorphism was associated with susceptibility to ovarian cancer and cervical cancer." (PMID 34582655, 2021). "On the other hand, their pooled results showed a protective effect for GG genotype of IL-6 -174 G>C polymorphism on development of ovarian cancer {Formatting Citation}." (PMID 34582655, 2021). "IL-6 is highly expressed in the serum and ascites of patients with ovarian cancer, and its upregulation is significantly associated with the poor prognosis." (PMID 35004308, 2021). "There was a significant differences between ovarian cancer and cervical cancer patients and controls for IL-6 -174 G>C variant." (PMID 34582655, 2021). "For example, the IL-6 expression associated with tumor progression, invasiveness and resistance to chemotherapy in ovarian cancer cells have been also extensively reported." (PMID 34096454, 2021). "Here, we evaluated the association of IL-6 -174G>C and -572 G>C polymorphisms with susceptibility to cervical and ovarian cancers in an Iranian population." (PMID 34582655, 2021).
ovarian carcinoma (continued). "Ovarian carcinoma-associated mesenchymal stem cells can activate the tumor cell stemness via activating IL6/STAT3 signaling." (PMID 33768003, 2021). "In this context, we demonstrated, using the ascites of patients with advanced serous papillifery ovarian cancer, a prevalence of M1 cells and an association between M1 macrophage polarization and high levels of IL-6, hepcidin, and ROS production." (PMID 33550983, 2021). "Screening for the IL-6 -174G>C and -572G>C polymorphisms in ovarian cancer and cervical cancer was performed in this study." (PMID 34582655, 2021). "There was a significant association of IL-6 -174G>C CC genotype (OR= 3.231, 95% CI: 1.130-9.239, p=0.029) and C allele (OR = 1.915; 95%CI: 1.266-2.896, p=0.002) with an increased risk of ovarian cancer." (PMID 34582655, 2021). "Reinartz derived a signal network model involving ovarian cancer cells and tumor associated macrophages (TAMs) linking IL-6, IL-10, and leukemia inhibitory factor (LIF) as cytokines that activate signal transducer and activator of transcription 3 (STAT3)." (PMID 34503128, 2021). "This study showed that the IL-6 -174G>C polymorphism was associated with ovarian cancer and cervical cancer risk." (PMID 34582655, 2021). "In animal models of ovarian cancer, plasma and/or central nervous system (CNS) IL-6 was found to be associated with reduced locomotion and depression-like behaviors." (PMID 33550983, 2021). "Additional clinical trials and the examination of clinical samples are warranted to evaluate the usefulness and to investigate the underlying mechanism of anti-IL-6 therapies in ovarian cancer." (PMID 32375852, 2020). "A study carried out in a mouse model has suggested that ovarian cancer-associated fibroblasts produce IL-6 in the OC microenvironment and induce differentiation of tumor stem cells, which contributes to postchemotherapy recurrences." (PMID 33062717, 2020). "In orthotopic and syngeneic murine models of ovarian cancer, increases in disease burden are associated with concomitant increases in IL-6 and platelet counts." (PMID 33142915, 2020). "Finding that activin signalling is needed for release of IL‐6 in vitro and in the TOV21G murine cachexia model, we investigated the possible association between activin A and IL‐6 in human ovarian cancer patients." (PMID 31436048, 2020). "Consistently, activity of IL-6 has been linked to the resistance of Cisplatin and Carboplatin drugs in ovarian cancer cells." (PMID 32245498, 2020). "In ovarian cancer, overproduction of both inteleukin-6 (IL-6) and thrombopoetin by the tumors are causative of thrombocytosis, which results in maintenance of tumor microvessel integrity and pericyte support in an autocrine feedback loop." (PMID 32842701, 2020). "Recent studies also propose that increased serum levels and peritoneal cavity levels of both IL-6 and IL-10 are associated with factors of worse prognosis in ovarian cancer patients." (PMID 32138790, 2020). "Levels of IL-6 were found to be significantly associated with clinical outcomes in patients treated with bevacizumab for ovarian cancer." (PMID 32759686, 2020). "A mild correlation between IL-6 or IL-1β levels and VTE was observed in pancreatic cancer patients, while a stronger association was reported for IL-6 and ovarian cancer." (PMID 30650562, 2019). "Ovarian cancer associated exosomes can also induce the production of IL-6 within monocytes through toll-like receptor (TLR) activation." (PMID 31409361, 2019). "In patients with ovarian cancer, elevated levels of serum IL-6 (P = 0.041) and IL-8 (P = 0.041) were associated with poorer initial response to paclitaxel." (PMID 30791431, 2019). "In vitro treatment of ovarian cancer cells with an anti-IL-6 therapy reduced tumor growththe tumor-associated macrophage infiltrate and angiogenesis." (PMID 29455640, 2018).
ovarian carcinoma (continued). "Among them, we focused on the cytokine IL-6 which has already been implicated in chemoresistance and angiogenesis in several malignancies including ovarian cancer." (PMID 29930760, 2018). "Coward showed that intensity of IL-6 staining in malignant ovarian cancer cells significantly associated with poor prognosis in a series of 221 patients." (PMID 29455640, 2018). "Increased expression of IL6 has been linked to ovarian cancer and poor outcome in several studies and has been examined as a potential prognostic marker." (PMID 28473707, 2017). "Here, we provide the first indication that Par3 is associated with ovarian cancer progression through the IL-6/STAT3 pathway." (PMID 27855669, 2016). "In ovarian cancers, the induction of IL-6 by the co-existence of an ARID1A-PIK3CA mutation has been shown to promote ovarian clear cell carcinoma." (PMID 27483433, 2016). "Recent studies revealed that elevated serum levels of IL-6 were significantly associated with the progression of malignancies, such as, ovarian cancer, esophageal cancer, and head and neck cancer." (PMID 25761055, 2015). "IL-6, which is present at high level in ovarian cancer ascites and associated with the generation of TAMs, is associated poor prognosis and chemoresistance." (PMID 24936477, 2014). "In ovarian cancer, increased levels of IL-6 in patients’ sera are linked to tumor progression, resistance to apoptosis and chemoresistance." (PMID 22583829, 2012). "IL-6 signaling cascade in ovarian cancer cells has been associated with the development of Taxol resistance." (PMID 21619709, 2011). "IL-6 can be secreted in ascites by ovarian cancer cells, tumor-associated macrophages and peritoneal mesothelial cells." (PMID 21619709, 2011). "A variety of tumor progression‐associated proteins are induced by IL‐6 in ovarian cancer." (PMID 40968783, 2026). "IL-6 was found to induce chemoresistance in ovarian cancer, and mesenchymal stromal cells, particularly cancer-associated fibroblasts (CAFs), were found to be the main source of IL-6 secretion in ovarian cancer." (PMID 38932405, 2024). "Furthermore, we screened the IL-6 inhibitory compounds using an in vitro cytotoxicity test against the ovarian cancer cell lines (A2780/SKOV3) and drug-resistant variants (A2780-Cis/SKOV3-TR) to assess their anticancer potential." (PMID 38998933, 2024). "SPARC expression could inhibit the production of interleukin-6 in ovarian cancer tissues and decrease levels of peritoneal metastasis caused by ovarian cancer." (PMID 35211625, 2022). "Besides, IL-6 induces the Mcl-1 anti-apoptotic protein expression, which is recurrently overexpressed in ovarian cancer, and it is associated with advanced tumor grade and poor survival in epithelial ovarian cancer." (PMID 34751020, 2022). "Of relevance for the aim of the present work, we have previously shown that RV counteracts the IL-6-induced inhibition of autophagy in ovarian cancer cells by rescuing the expression of ARH-I, an effect linked to the opposite regulation of miRNAs targeting the mRNA of this protein." (PMID 35565270, 2022). "In a preclinical ovarian cancer model examining the role of IL-6 in cancer-related cachexia, they discovered severe weight loss and progressive muscle wasting due to altered metabolism and elevated levels of IL-6, p-STAT3, and reduced p-Akt levels." (PMID 35159388, 2022). "Since then, a paracrine circuit involving IL-6, which increases the levels of fibrinogen and thromboplastin thereby causing thrombocytosis, has been found to be associated with increased thrombotic risk in patients with ovarian cancer and other neoplasms." (PMID 33550983, 2021). "An additional inflammatory mediator is Cyr61 (cysteine-rich protein 61), a 40 kDa secreted matrix protein that stimulates proliferation, production of inflammatory mediator IL-6, prevents carboplatin-induced apoptosis and is associated with poor prognosis in ovarian cancer patients." (PMID 34503128, 2021).
ovarian carcinoma (continued). "However, their results failed to support an association between selected polymorphisms at IL-1α, IL-β, IL-6, IL-10, or IL-18 gene and increased risk of ovarian cancer in USA." (PMID 34582655, 2021). "However, a few studies have been conducted to determine the association of IL-6 polymorphisms with ovarian cancer and cervical cancer risk." (PMID 34582655, 2021). "Similarly, pooled data in a meta-analysis supported that recessive genetic model (GG vs. GC+CC) of IL-6 -174 G>C polymorphism is significantly associated with increased survival of women with ovarian cancer, peritoneal cancer and other malignancies." (PMID 34582655, 2021). "Moreover, statistically significant association of the IL-6 -174G>C CC genotype (OR= 3.162, 95% CI: 1.094-9.141, p=0.034) and C allele (OR = 1.724; 95%CI: 1.129-2.633, p=0.012) with the increased risk of ovarian cancer was found." (PMID 34582655, 2021). "Thus, in this study the association of IL-6 -174G>C and -572G>C polymorphisms with ovarian cancer and cervical cancer in Iranian women was evaluated." (PMID 34582655, 2021). "In a larger cohort of patients with advanced cancer at diagnosis before antineoplastic treatment, where patients with ovarian cancer showed the most severe anemia, low hemoglobin levels were associated with high hepcidin and ferritin levels, which were positively correlated with IL-6." (PMID 33550983, 2021). "Also, some GWA studies investigated the association of the IL-6 gene polymorphisms with thyroid cancer, ovarian cancer, pancreatic cancer, neuroblastoma and renal cell carcinoma." (PMID 33684135, 2021). "Moreover, a significant association between plasma IL-6 and vegetative depression, disability, sleep disturbances, and fatigue has been demonstrated in patients with ovarian cancer at the time of surgery." (PMID 33550983, 2021). "Thus, the IL-6 -174G>C polymorphism is a potential to be evaluated as prognostic biomarkers predicting or identifying cases of high risk of ovarian cancer and cervical cancer." (PMID 34582655, 2021). "Thus far, EMT in ovarian cancer cells exposed to malignant ascites was linked to the activity of the IL-6/IL-6R axis and signaling through the JAK2-STAT3 pathway." (PMID 30609691, 2019). "Indeed, in patients with ovarian carcinoma, elevated levels of serum IL-6 and IL-8 were associated with significantly poor prognosis/chemoresistance." (PMID 30791431, 2019). "A phase II study suggested that the extent of IL-6 increase in the plasma during treatment was associated with an inferior outcome in patients with rectal and ovarian cancer after bevacizumab and chemoradiation treatment, and an inferior outcome in patients with advanced HCC after sunitinib therapy." (PMID 27903982, 2017). "Moreover, an increasing level of IL-6 is significantly associated with thrombocytosis, and blocking IL-6 leads to progression-free survival and overall survival benefits in patients with ovarian cancer." (PMID 29163847, 2017). "Although not only ovarian cancer cells but tumor-associated macrophages have been reported to produce IL-6, it remains debatable whether increased IL-6 levels in patients with ovarian cancer are produced by the tumor itself or mainly by host tissues." (PMID 25658637, 2015). "IL6 has been associated with progression in multiple cancer types, including ovarian cancer." (PMID 23369187, 2013). "In addition, high level of IL-6 in ovarian cancer ascites has been associated with shorter progression-free survival." (PMID 24093089, 2013). "However, they consider Il-6 as a useful diagnostic tool in the diagnosis of ovarian cancer." (PMID 37373969, 2023). "Additionally, the activation of oxidative phosphorylation has been reported to be linked with CDDP resistance in ovarian cancer by stimulating the production of pro-inflammatory cytokines such as IL-6 and IL-8, which favor the expression of membrane pumps involved in the extrusion of CDDP." (PMID 37916165, 2023).